HMGB1 (high mobility group box 1)
Diseases named in the same sentence as HMGB1 in open-access papers (continued):
Sharing a sentence is not in itself a finding about the gene and the disease.
tumor (continued). "Subsequently, scientists discovered that HMGB1, a natural activator of TLR2, with high mobility group box 1 secreted by tumor cells upon death." (PMID 40727443, 2025). "Based on these results, we suggest that radiation enhances the exposure of CRT and the secretion of HMGB1, dsDNA, ATP, HSP70, and HSP90 by tumor cells, thereby increasing the immunogenicity of FA." (PMID 40135850, 2025). "ICD is characterised by calreticulin exposure, HMGB1 release, and activation of the cGAS-STING pathway, which together prime anti-tumour immunity." (PMID 41226343, 2025). "To verify the effect of miR-497/SK-NBs on ICD at the tumor site, we performed immunofluorescent, flow cytometer and ELISA to evaluate the density of CRT and HMGB1 in tumor masses." (PMID 41583493, 2025). "Previous studies have reported similar self-amplifying loops between HMGB1 and TLR4 in other malignancies, where sustained activation of this axis enhances tumor aggressiveness." (PMID 40559922, 2025). "To confirm the role of HMGB1 in promoting M1 macrophage polarization, we transfected MC38 with lentivirus containing HMGB1 knockout constructs to knock down HMGB1 in MC38 and established corresponding subcutaneous tumor models in mice." (PMID 40082916, 2025). "The NanoTAC (+L) group presented markedly greater percentages of surface CRT-expressing tumor cells (CD45−CRT+), accompanied by substantial extracellular release of HMGB1 and HSP70." (PMID 40998785, 2025). "Mechanistically, NETs release high-mobility group box 1 (HMGB1), which activates TLR9 signaling in tumor cells, promoting their proliferation and metastatic competency." (PMID 40995363, 2025). "Extracellular HMGB1 upregulates the PD-L1 expression by binding to RAGE, thereby aiding tumor immune evasion." (PMID 40389855, 2025). "We then found from GEPIA database that PRC1 had a positive expression correlation with ICD markers (CRT and HMGB1) and the immune checkpoint gene CD274 in tumor tissues from COAD and READ patients." (PMID 40847353, 2025). "To this end, we constructed a subcutaneous xenograft tumor model of CRC in athymic nude mice, which included a sh-HMGB1 group and a control group (sh-NC), and the tumor-bearing mice were treated with 10 Gy X-ray irradiation." (PMID 41164196, 2025). "ELISA analysis revealed that tumor spheres released significantly more S100A8/9 and HMGB1 into the tumor microenvironment than adherent cells." (PMID 40647457, 2025). "Preclinically, docetaxel has been shown to induce the release of the alarmin high mobility group box 1 protein (HMGB1), which interacts with the TIM-3 receptor to subvert immune responses triggered by dying tumor cells." (PMID 40552922, 2025). "Immunostimulatory DAMPs include ATP, which is secreted via autophagy-dependent mechanisms, and nuclear or cytoplasmic proteins, such as annexin A1 (ANXA1) and high mobility group box 1 (HMGB1), which are passively released from dying tumor cells." (PMID 40004078, 2025). "HMGB1 promotes the activation of the PI3K/AKT signaling pathway, leading to the upregulation of HIF-1α, which in turn enhances VEGF expression, inducing tumor angiogenesis and cell migration." (PMID 40396172, 2025). "Namely, CLR translocation and HMGB1 release, markers of immunogenic cell death, were detected after ECT in both tumor models." (PMID 40007542, 2025). "Thus, HMGB1 could be a potential prognostic biomarker for distant tumor metastasis." (PMID 40331953, 2025). "Activation of GSDMC2/3/4 induces tumor cell pyroptosis and facilitates the release of HMGB1, which enhances the expression of CXCL2 in tumor cells." (PMID 40213993, 2025). "Upon lysis, tumor cells infected with rNDV release substantial quantities of DAMPs, such as calreticulin (CRT), ATP, and high-mobility group box 1 (HMGB1)." (PMID 41479917, 2025).
tumor (continued). "Consistent with our in vitro findings, simvastatin-treated mice showed significantly higher serum levels of HMGB1 and a greater proportion of CRT+ tumor cells compared to controls, along with increased recruitment of conventional DCs to the tumor." (PMID 41339438, 2025). "GSDMC2/3/4‐mediated pyroptosis in tumor cells leads to the release of high mobility group protein B1 (HMGB1), which enhances the expression of chemokine attractant C‐X‐C motif chemokine 2 (CXCL2) in surrounding tumor cells." (PMID 40213993, 2025). "The combined treatment of HMGB1 and GEM with RSL3 significantly suppressed tumor proliferation in in vivo experiments, immunohistochemistry also confirmed this result." (PMID 40495163, 2025). "HMGB1, a TLR-4 ligand, can induce tumor chemoresistance by activating NF-κB through the TLR4/MyD88 pathway." (PMID 40404908, 2025). "HMGB1 is a nuclear protein that maintains chromatin structure; its role in ICD is to amplify inflammation, and this function is activated by OV-mediated tumor lysis." (PMID 41314288, 2025). "When HMGB1 was knocked down, the supernatant from ADVNE− and ADVPPE-treated tumor cells lost the ability to induce the M1 polarization of macrophages." (PMID 40082916, 2025). "The interaction between HMGB1 and RAGE then enhances tumor cell proliferation by advancing the cell cycle (Cyclin D1, Cyclin E1, PCNA) through NF-κB pathways." (PMID 40244228, 2025). "Tumors undergoing lipid oxidative stress release immunogenic cell death signals such as high mobility group box 1 (HMGB1), a mechanism critical for GPX4-mediated tumor targeting." (PMID 40001204, 2025). "Radiation promotes the release of danger signals such as high mobility group box 1 (HMGB‐1) from PDAC cells, facilitates phagocytosis of tumor cells by dendritic cells, and enhances tumor antigens to CD8 T cells." (PMID 40385329, 2025). "Lactate stimulates high-mobility group box 1 (HMGB1) expression and secretion by macrophages, promoting ERK, EMT, and Wnt signaling pathways activation in tumor cells." (PMID 40361394, 2025). "RT released HMGB1 from tumor cells that induce high TNF-α and low levels of IL-10 secretion from M1-type macrophages that exert drastic anti-tumor activity." (PMID 40141437, 2025). "Inhibiting the nucleo-cytoplasmic translocation of HMGB1, particularly through ICM treatment, reduces STAT3 activation and PD-L1 expression, leading to decreased tumor growth in vivo." (PMID 40389855, 2025). "ICD is marked by the membrane translocation of calreticulin (CRT) and the release of high mobility group protein B1 (HMGB1), ATP, heat shock proteins (HSPs), and ANXA1, all of which play roles in amplifying immune responses against tumor cells." (PMID 39987121, 2025). "Therefore, HMGB1 may become a regulatory target for anti-tumor therapy." (PMID 40356601, 2025). "Necroptosis, initiated by Receptor-Interacting Protein Kinase 1 (RIPK1)/RIPK3-MLKL signaling, leads to the release of High Mobility Group Box 1 (HMGB1) and supports cross-presentation of tumor antigens, thus linking cell death to immune surveillance." (PMID 41235238, 2025). "The HMGB1/RAGE axis plays a crucial role in regulating angiogenesis, and its inhibition has been demonstrated to curb tumor angiogenesis and progression." (PMID 38529373, 2024). "Rutaecarpine, the active compound in Evodia rutaecarpa, has been identified as a suppressor of the HMGB1/RAGE pathway, exhibiting the potential to hinder tumor growth and angiogenesis." (PMID 38529373, 2024). "Certain functional RNAs, including long non-coding RNAs and microRNAs, regulate the expressions of HMGB1/RAGE and impact tumor cell proliferation." (PMID 38529373, 2024). "The predictive value of serum HMGB1, IDO and ESCC serum tumor markers (CEA and SCC-Ag) on the clinical progression of ESCC was analyzed." (PMID 39314628, 2024).
tumor (continued). "In HCC, HMGB1 triggers M2 macrophage polarization through the TLR2/NOX2/autophagy axis, a transformation that promotes tumor growth via upregulation of IL-10 expression." (PMID 38529373, 2024). "Correlation analysis on 33 tumor types from the TCGA database revealed a strong positive correlation between METTL3 and HMGB1 expression in 31 tumor types, including BLCA." (PMID 38504159, 2024). "We postulated that HSP90, HMGB1, and S100A9 have the potential to be predictive biomarkers for supporting tumor metastasis categorization using histopathology." (PMID 39768997, 2024). "Having made sure that HMGB1 can be considered a TREM-1 ligand, we investigated its ability to activate cytotoxic lymphocytes capable of lysing HLA-negative tumor cells." (PMID 38203798, 2024). "The authors showed that binding of miR-142-3p to the 3′ non-coding region (3′UTR) in HMGA1, HMGA2, HMGB1, and HMGB3 mRNAs leads to apoptosis of tumor cells, as well as to decreased proliferation, migration, and invasion." (PMID 39062899, 2024). "Although many chemical drugs and small RNAs have been found to regulate the HMGB1/RAGE axis and inhibit tumor cell metastasis and invasion, their research is still in the early stage and further studies are needed to validate their efficacy and safety." (PMID 38529373, 2024). "As we began to view HMGB1 as a MUFA-regulated protein, it became essential to identify its role in the tumor immune landscape." (PMID 39100092, 2024). "Supporting the activation of immunogenic apoptosis, we observed a significant increase in plasma HMGB1 levels and enhanced exposure of calreticulin on the surface of B16F10 tumor cells (5th column)." (PMID 39681571, 2024). "Owing to the synergistic effects of SMAC and DOX, higher expression levels of DAMPs such as CRT, HMGB1, and ATP in Aposome-treated CT26 tumor cells were observed compared to DOX- and DOXIL-treated groups." (PMID 39769944, 2024). "One pathway is that HMGB1 binds to the cell membrane surface receptor RAGE to activate its pathway and up-regulate the expression of VEGF, thus promoting tumor proliferation." (PMID 38577597, 2024). "Since both HMGB1 and HMGN1 are known to trigger DC maturation, these results substantiate the notion that DAMPs/alarmins released by tumor cells in response to LTX-315 treatment contribute to DC maturation." (PMID 38545099, 2024). "cDAMPs consist of immune-stimulating molecules such as CRT, ATP, HMGB1, and HSP, which are expressed prior to tumor cell death." (PMID 38745666, 2024). "In the current study, we examined The Cancer Genome Atlas (TCGA, n = 542) and the Clinical Proteomic Tumor Analysis Consortium (CPTAC, n = 115) Lung adenocarcinoma (LUAD) datasets to view the relationship between lipid metabolism and HMGB1 in NSCLC tumors." (PMID 39100092, 2024). "It suggested that HMGB1 and HSP90 are promising predictive biomarkers for tumor metastasis discrimination, and that combined analysis of DAMP biomarkers is not necessary." (PMID 39768997, 2024). "HMGB1, which binds to TLR4, aids in tumor-antigen processing and presentation, enhancing the anti-tumor immune response through its effect on DCs." (PMID 39456655, 2024). "This reaction enabled the generation of a large amount of ROS in the tumor environment to enhance the PDT to improve the ICD by generating calreticulin (CRT), adenosine triphosphate, and high mobility group protein B1 (HMGB1)." (PMID 40808797, 2024). "Chiba and colleagues highlighted the ability of TIM3 to bind and sequester HMGB1 away from TLR, thus avoiding the sensing of tumour-derived nucleic acids bound to HMGB1 itself." (PMID 38504978, 2024). "Next, we will expand the sample size and construct a tumor immune microenvironment model to further explore the role and related mechanisms of HMGB1 and IDO in tumor immunity." (PMID 39314628, 2024).
tumor (continued). "Phagocytosis of tumor cells undergoing ferroptosis is triggered by three important DAMPs in bone marrow-derived dendritic cells: calreticulin (CRT), high-mobility group protein B1 (HMGB1), and adenosine triphosphate (ATP)." (PMID 38292937, 2024). "As resident tumor macrophages expressing MKI67, CDK1, and CDC45, HMGB1, and others, Prolif-TAMs were likely pro-inflammatory, profibrotic, and promoting tumor progression." (PMID 39184073, 2024). "Mechanistically, siRNA silencing of HMGB1 abolished PRKN IFN gene expression in human (PC3) and murine (TRAMP-C2) tumor cell types." (PMID 39213189, 2024). "This is, to our knowledge, the first study to identify increased levels of HMGB1 in patients with MF, revealing the participation of this DAMP in the inflammatory milieu that characterizes this neoplasm." (PMID 39391311, 2024). "Another pathway is that HMGB1 binds to toll-like receptors, activating the MAPK signaling pathway to induce angiogenesis, promoting tumor cell proliferation, invasion, and metastasis." (PMID 38577597, 2024). "Among these, IL-1B, IL-6, TNF, CXCLs, TGFB1, HMGB1, STAT3, and STAT5 have been reported to contribute to tumor formation." (PMID 39156107, 2024). "Tumor-driven factors like TNF-α, GM-CSF, HMGB1, IL-6, CCL20, and hypoxia boost PD-L1 levels in neutrophils, dampening immune responses, particularly T cells." (PMID 38760815, 2024). "In summary, additional investigation is warranted to comprehend the involvement and regulatory mechanisms of the HMGB1/RAGE axis in tumor metastasis, which will offer novel insights and approaches for advancing tumor treatment." (PMID 38529373, 2024). "Therefore, HMGB1 might serve as a regulatory target for drug resistance and a prognostic marker for malignant tumors, it has a promising clinical application as a target for tumor therapy and various HMGB1-targeted drugs have been developed recently." (PMID 37897664, 2024). "Immunogenic cell death is a rare form of immunostimulatory cell death that can reactivate tumor-specific immune responses and is characterized by the release of DAMPs, including exposure to CRT on the cell surface and release of ATP and HMGB1." (PMID 39014462, 2024). "TAMs upregulate Gfi‐1 in tumor cells by TGF‐β secretion, which ultimately leads to reduced sensitivity of tumor cells to gemcitabine by inhibiting HMGB1 (high mobility group box 1) and CTGF (connective tissue growth factor) expression." (PMID 37994401, 2024). "This is due to the upregulation of PD-L1 in tumor cells and the infiltration of myeloid-derived suppressor cells (MDSC) mediated by HMGB1, which counteracts the infiltration of cytotoxic CD8+T cells dependent on CXCL10." (PMID 38292937, 2024). "Following various treatments, we conducted immunofluorescence staining to analyze the expression of HMGB1 and CRT in tumor tissues." (PMID 38715912, 2024). "Immunogenic cell death inducers trigger release of HMGB1, which by binding to TLR4, promotes the processing and presentation of tumor antigens by inhibiting their premature lysosomal degradation." (PMID 39417004, 2024). "In the present study, we further demonstrated that SKN-induced ICD in CT26 cells in a dose-dependent manner by measuring levels of ROS, ATP, HMGB1, and CRT, providing a strong evidence for using SKN in producing the in situ tumor vaccines." (PMID 38807377, 2024). "Tumor endothelial cells (ECs) secrete HMGB1 and increase the expression of RAGE, promoting the angiogenic capacity of tumor ECs." (PMID 38529373, 2024). "The top GRNs in primary tumors were TCF4, TAGLN2, FOXK1, and BHLHE41, whereas the top upregulated GRNs in recurrent tumor cells were FOXP2, FOXD1, SIX4, and HMGB1." (PMID 39711559, 2024). "In our previous study, CTT induced tumor cell necrosis and promoted the release of a large amount of DAMPs including HSP70, HMGB1 and CRT, which upregulate the expression of adhesion molecules on endothelial cells to promote neutrophil adhesion." (PMID 39555061, 2024).
tumor (continued). "The experimental results showed that tumor cells in the HPNDs@EcN + US group had stronger CRT cell exposure and HMGB1 exocytosis than the control group." (PMID 38610042, 2024). "The rupture of tumor cells undergoing pyroptosis releases a number of inflammatory factors, including IL-18, IL-1β, HSP, ATP, and HMGB1." (PMID 39575419, 2024). "Its targets have been reported to be IL-8, COL1A1, ADAM9, HMGB1, and SLC2A3, and inducing mir-129-5p overexpression in tumor cells reduced malignant characteristics, including cell proliferation, migration, and invasion." (PMID 39797181, 2024). "Meanwhile, we observed an increased secretion of high-mobility group protein 1 (HMGB1) in the culture supernatant and expression of calreticulin (CRT) on the tumor cell surface after treatment with E/S Lip and P-E/S Lip." (PMID 39068444, 2024). "Combining the assessment of HMGB1 concentrations in patient plasmas with other ICD-relevant parameters such as CALR expression and eIF2α phosphorylation in tumor biopsies should inform more accurately on the anticancer immune response." (PMID 39572927, 2024). "Different mechanisms have been identified as drivers of NET formation, indirectly by the immune cells in the TME, or directly by the tumor cells by releasing various molecules such as IL-1, IL-6, IFN, TNF-α, C3a, HMGB1, or G-CSF." (PMID 39001538, 2024). "Silencing of HMGB1 with siRNA in the doxorubicin-treated CT26 or MCA205 tumor model and irradiated EG7 dying tumor cells disrupts antigen presentation and inhibits the priming of T cells." (PMID 38725632, 2024). "In this review, we outline the multifaceted functions of the HMGB1/RAGE axis, which encompasses tumor cell proliferation, apoptosis, autophagy, metastasis, and angiogenesis." (PMID 38529373, 2024). "HMGB1 acts as DAMP and is recognized by dendritic cells to elicit a potent tumour-specific T-cell response." (PMID 39372406, 2024). "In particular, CISE NPs‐treated Renca tumor cells showed the highest CRT exposure, HMGB1 release, and ATP secretion, indicating an intensified immunogenic death effect was induced." (PMID 38884220, 2024). "Surprisingly, MCM3 was positively correlated with the expression of several immune checkpoint molecules, such as HMGB1, BTN3A2, CD276, and VEGFA, in almost all of the tumours." (PMID 38698811, 2024). "Expression of four genes decreased after CaPa, TNFSF18, coding for GITRL, HMGB1, TNFSF4, coding for OX-40 L and HLA-A, all involved in the positive regulation of anti-tumor immune response." (PMID 38581044, 2024). "Serum HMGB1 and IDO have a synergistic effect, they inhibit immune function and promote tumor progression in ESCC patients, and also lead to poor prognosis." (PMID 39314628, 2024). "Compared with the groups treated with PBS, IR780, Tanespimycin, TISN, and IR780+L group, TISN+L group demonstrated a significantly enhanced release of high mobility group protein B1 (HMGB1) and ATP from CT26 tumor cells." (PMID 39525955, 2024). "HMGB1 exerts potent pro-inflammatory effects by binding to TLR4 on DC, promoting the efficient processing and cross-presentation of tumor antigens derived from dying cells." (PMID 38994937, 2024). "The HMGB1-RAGE interaction modulates cellular metabolism and promotes tumor proliferation by increasing the generation of ATP in the mitochondria." (PMID 39008169, 2024). "An increased expression of HMGB1 following RCT correlates with higher overall survival and decreased tumor recurrence." (PMID 37857049, 2023). "The treatment led to a tumor apoptosis rate of 35.1 ± 1.8 %, detected with Annecin V-FITC, and an increase in CRT-positive cells and of the HMGB1 release." (PMID 37238966, 2023). "Compared with the control group, free Dox elicited an increasing release of intratumoral, high-mobility group box-1 (HMGB1), as well as overexpression and exposure of calreticulin (CRT) on the surface of tumor cells." (PMID 37620331, 2023).